RNU4-56P (RNA, U4 small nuclear 56, pseudogene)
Gene: Small nuclear RNA gene on chromosome 3 (39,970,125 to 39,970,266, forward strand). Ensembl gene ENSG00000201570.
Homologues: Orthologues: chimpanzee U4 (100% identical), macaque U4 (92% identical), guinea pig U4 (77% identical), dog U4 (63% identical), rabbit U4 (60% identical), rat LOC120096855 (59% identical), dog U4 (57% identical). Paralogues in human: RNU4-67P (83% identical), RNU4-68P (82% identical), RNU4-58P (82% identical), RNU4-13P (81% identical), RNU4-7P (81% identical), RNU4-42P (79% identical), RNU4-44P (79% identical), RNU4-45P (78% identical), RNU4-80P (78% identical), RNU4-8P (77% identical), RNU4-23P (77% identical), RNU4-31P (77% identical), and 81 more.